RNU6-351P (RNA, U6 small nuclear 351, pseudogene)
Gene: Small nuclear RNA gene on chromosome 4 (104,974,672 to 104,974,771, forward strand). Ensembl gene ENSG00000251906.
Homologues: Orthologues: chimpanzee U6 (98% identical), macaque U6 (89% identical), guinea pig U6 (76% identical). Paralogues in human: RNU6-414P (79% identical), RNU6-824P (77% identical), RNU6-843P (77% identical), RNU6-1094P (76% identical), RNU6-1116P (76% identical), RNU6-1287P (76% identical), RNU6-24P (76% identical), RNU6-1056P (75% identical), RNU6-1060P (75% identical), RNU6-1270P (75% identical), RNU6-527P (75% identical), RNU6-797P (75% identical), and 1284 more.